GSK3B (glycogen synthase kinase 3 beta)
Diseases named in the same sentence as GSK3B in open-access papers (continued):
Sharing a sentence is not in itself a finding about the gene and the disease.
diabetic retinopathy (1 paper, 2020). "Therefore, we speculate that feedback regulation between MAPK-Akt and GSK3β signaling pathways may be a potential target for Hyp in the treatment of diabetic retinopathy." (PMID 32547397, 2020).
diffuse large B-cell lymphoma (1 paper, 2024). "In diffuse large B-cell lymphoma (DLBCL), exosomal ENO2 enhances glycolytic metabolism, activating the GSK3β/β-catenin/c-Myc signaling pathway, which in turn promotes macrophage M2 polarization." (PMID 39309441, 2024).
E. coli infection (1 paper, 2025). "In this study, the phosphorylation of GSK-3β (Ser9) decreased as the duration of E. coli infection increased, and Co-IP and immunofluorescence revealed the interaction between GSK-3β and NRF2." (PMID 41413615, 2025). "E. coli infection activates GSK-3β through dephosphorylation at Ser9, active GSK-3β binds and degrades NRF2 via the proteasome pathway, and NRF2 suppression disrupts antioxidant defenses (SLC7A11/GPX4 and GCLC/GSH) and iron homeostasis (FTH1), triggering ferroptosis in BEECs." (PMID 41413615, 2025).
edema (1 paper, 2015). An abnormal accumulation of fluid beneath the skin, or in one or more cavities of the body. "It is known that PHA 543613 is a potent and selective α7R agonist, which has been shown to reduce induced brain edema in a mouse model through the inhibition of GSK-3β." (PMID 26389120, 2015).
embryonic carcinoma (1 paper, 2020). "Curcumin was shown to suppress Wnt/B-catenin signaling by activating both Oct4 and glycogen synthase kinase 3B (GSK-3B) in both human embryonic kidney 293T cells and NCCIT human embryonic carcinoma cells." (PMID 32695811, 2020).
emesis (1 paper, 2022). "Similarly, the antiemetic GSK-3β inhibitor AR-A014418 was found to be less efficacious against quinpirole-evoked emesis, compared with apomorphine." (PMID 35444553, 2022).
emphysema (1 paper, 2018). "Nevertheless, it is unknown whether AMPK competes with Wnt ligands or GSK3β in phosphorylating β‐catenin thereby modulating Wnt signal during the development of emphysema." (PMID 29659176, 2018).
endometritis (1 paper, 2025). An acute or chronic, usually bacterial infectious process affecting the endometrium. "Modulating GSK-3β/NRF2 holds promise as a potential therapeutic strategy for alleviating endometritis induced by E. coli." (PMID 41413615, 2025). "Although E. coli is the primary etiological agent studied here, future work should assess whether GSK-3β/NRF2-driven ferroptosis extends to other endometritis pathogens (e.g., Trueperella pyogenes)." (PMID 41413615, 2025).
energy metabolism disorder (1 paper, 2020). "We hypothesized that ICA improves brain mitochondrial energy metabolism disorder, and its mechanism is related to the PI3K/Akt/GSK-3β signaling pathway." (PMID 32341897, 2020).
epithelioid sarcoma (1 paper, 2021). An aggressive malignant neoplasm of uncertain differentiation, characterized by the presence of epithelioid cells forming nodular patterns. "We evaluated and demonstrated, for the first time, that the inhibition of GSK-3β has an effect on epithelioid sarcoma cells’ proliferation." (PMID 34681807, 2021).
extrahepatic cholestasis (1 paper, 2024). Impairment of the bile flow caused by an obstruction in the portion of the bile duct system located outside of the liver. "In this study, bile duct ligation was conducted to induce an animal model of extrahepatic cholestasis, targeting the PI3K/AKT/GSK-3β signaling pathway and intestinal flora, to investigate the therapeutic effect of SAL on obstructive cholestatic liver fibrosis and its mechanism." (PMID 38808258, 2024).
facioscapulohumeral muscular dystrophy (1 paper, 2021). An autosomal dominant disorder affecting the skeletal muscles of the face, scapula, and upper arm. "This could be a good resource for DMD, since ESR2 induces muscular differentiation in facioscapulohumeral muscular dystrophy and GSK3b could help to reduce muscular degeneration." (PMID 33918694, 2021).
familial Alzheimer disease (1 paper, 2014). A degenerative disease of the brain that causes gradual loss of memory, judgment, and the ability to function socially. "Lithium, a specific inhibitor of GSK-3α and GSK-3β, reduces Aβ production by interfering with APP cleavage at the γ-secretase step and is found to reduce Aβ production in the mice expressing pathogenic familial Alzheimer's disease." (PMID 24983010, 2014).
fluorosis (1 paper, 2024). "In addition, various inflammatory indicators (TNF-α, IL-1β, NF-κB), and other fluorosis-related indicators (Mag, GSK3β) were also included to assess spinal cord injury in fluorosis rats." (PMID 39687171, 2024).
focal segmental glomerulosclerosis (1 paper, 2025). A renal disorder characterized by sclerotic lesions in the glomeruli. "In kidney biopsies from patients with primary focal segmental glomerulosclerosis (FSGS), increased expression of phosphorylated GSK3β in podocytes was observed." (PMID 40526103, 2025).
gastric adenoma (1 paper, 2024). A neoplastic polyp that arises from the stomach. "Elevated TNS4 expression has been shown to promote the EMT process through AKT/GSK-3β signaling and is proposed to correlate with the development and progression of gastric adenomas, a process purportedly triggered by Hp infection." (PMID 38542354, 2024).
graft versus host disease (1 paper, 2020). An immune system disorder that occurs after allogeneic hematopoietic stem cell transplant and is a reaction of donor immune cells against host tissues. "The results of this study correlate with previous findings that GSK-3β activation has been found to be significant in mice with allograft rejection diseases, such as graft-versus-host disease (GVHD)." (PMID 32521784, 2020).
HCMV infection (1 paper, 2024). "Lastly, we would like to highlight the fact that SPOC1 was found to be decreased in a GSK-3β-dependent manner during later times of HCMV infection." (PMID 38543731, 2024). "The GSK-3β-dependent degradation of SPOC1 observed during HCMV infection may therefore represent a viral countermeasure of the repressive effects of SPOC1 on late viral transcription." (PMID 38543731, 2024).
hematoma (1 paper, 2023). A hematoma is a collection of blood from a vascular structure into an extravascular space. "In our experimental model of ICH, GSK3β was phosphorylated at Tyr216 in the peri-hematoma area, suggesting that this hemorrhagic injury could induce catalytic activity of GSK3β, possibly via upregulation of the PERK signal pathway." (PMID 36792604, 2023).
hereditary spastic paraplegia (1 paper, 2018). Hereditary spastic paraplegias (HSP) comprise a genetically and clinically heterogeneous group of neurodegenerative disorders characterized by progressive spasticity and hyperreflexia of the lower limbs. "Another study uncovered the therapeutic potential of GSK‐3β pathway inhibition to restore neurodevelopmental defects in hereditary spastic paraplegia (HSP) patients with SPG11 mutations." (PMID 29997171, 2018).
heroin addiction (1 paper, 2022). "Our present study identifies that GSK-3β inhibitors may have the potential therapeutic value in the treatment of heroin addiction." (PMID 35832395, 2022).
hyperparathyroidism (1 paper, 2016). Hyperfunction of the parathyroid glands resulting in the overproduction of parathyroid hormone. "The results suggest that inhibition of GSK‐3β increases trabecular bone volume but not cortical bone volume in adenine‐induced uremic mice with uncontrolled hyperparathyroidism." (PMID 27803315, 2016).
hyperphosphatemia (1 paper, 2024). Abnormally high level of phosphate in the blood. "The HypoC in combination with hyperphosphatemia induced downregulation of GSK3β phosphorylation (0.6 ± 0.09 and 0.7 ± 0.07-fold decrease, respectively, vs. CTRL." (PMID 37819413, 2024).
hypertriglyceridemia (1 paper, 2023). A laboratory test result indicating elevated triglyceride concentration in the blood. "Investigating the involvement of IL-6 and IL-10 in the activation of STAT3 and NF-κB pathways and in the regulation of endocytosis via GSK3β inhibition or actin filament rearrangements could provide a deeper understanding of the increased BBB permeability seen in hypertriglyceridemia." (PMID 36882782, 2023).
hypogonadotropism (1 paper, 2022). "The diminution of the key steroidogenic enzymes and the resultant decline in P4 and T levels suggests that HFD-HF diet-induced hypogonadotropism and a compromised Wnt2/GSK3β/β-catenin pathway disrupt the steroidogenic machinery in the ovary of adult rats." (PMID 36359843, 2022).
hypospadias (1 paper, 2024). Hypospadias is the displacement of the urethral meatus on the ventrum of the penis. "We utilized RT‐PCR and Western blot techniques to investigate the Wnt signaling pathway and observed a significant reduction in both mRNA and protein levels of SOX9, Wnt3a, LEF1, GSK3β, NF‐κB, TCF1, and cyclin D1 in the samples of hypospadias." (PMID 40626133, 2024).
ileitis (1 paper, 2025). "The effects of fidaxomicin on ileitis and ileal fibrosis were abolished by lentiviral Pdgfrb and Gsk3b overexpression." (PMID 40398622, 2025).
infertile (1 paper, 2014). "Materials and Methods: WNT3a protein concentration and GSK3-β gene expression levels were measured and compared between two groups of infertile men." (PMID 25031575, 2014).
insulin-resistant diabetes (1 paper, 2023). "That perspective arose from familial studies of insulin-resistant diabetes, which established that GSK3β is required for insulin signal transduction." (PMID 37895969, 2023).
intellectual disabilities (1 paper, 2023). "The introduction of a functional Cr transporter in the CTD-rescue organoids leads to a reduction of GSK3β activation, a restoration of the SOX2 progenitor marker level, as well as of the highlighted proteins linked to intellectual disabilities such as PAK1 and MAP1B." (PMID 37830910, 2023).
intestinal infection (1 paper, 2014). "S. Typhimurium intestinal infection in a murine model induces the phosphorylation of GSK-3β which, in turn, induces the phosphorylation of β-catenin and results in the translocation of NF-κB to the nuclease." (PMID 26664916, 2014).
intracranial hemorrhage (1 paper, 2024). Bleeding within the SKULL, including hemorrhages in the brain and the three membranes of MENINGES. "Given the critical role of ferroptosis in intracranial hemorrhage, these results may reveal a novel SAA-BASED therapy for patients with ICH, and the promotion of NRF2 activation through the Akt /GSK-3β pathway may be developed as a promising treatment for ICH." (PMID 38816543, 2024).
intraepithelial neoplasia (1 paper, 2015). A precancerous neoplastic process that affects the squamous, glandular, or transitional cell epithelium without evidence of invasion. "Also, it has been proposed that the activation of the Wnt/β-catenin pathway in intraepithelial neoplasia in Lkb1−/− mice involves the inactivation of Gsk3β complex by Par1A." (PMID 26056085, 2015).
Invasive lobular carcinoma (1 paper, 2009). "Five sections of histological confirmed Invasive lobular carcinoma (ILC) of breast were also analyzed for E-cadherin, Slug and GSK3β staining." (PMID 19751508, 2009).
ischemic cardiomyopathy (1 paper, 2021). Ischemic cardiomyopathy is a cardiomyopathy in which a weakness in the muscle of the heart due to inadequate oxygen delivery to the myocardium with coronary artery disease being the most common cause. "We found that phosphorylation of GSK3β at S389 was increased both in dilated and ischemic cardiomyopathy hearts." (PMID 34948382, 2021). "We first investigated if phosphorylation of GSK3β is dysregulated in left ventricular samples of explanted hearts from patients with end-stage dilated or ischemic cardiomyopathy." (PMID 34948382, 2021).
kidney cancer (1 paper, 2009). Primary or metastatic malignant neoplasm involving the kidney. "Immunohistochemical detection of GSK-3β nuclear accumulation could be a useful diagnostic method for pathological verification of kidney cancer." (PMID 19920820, 2009). "However, the role of GSK-3β in kidney cancer remains unknown." (PMID 19920820, 2009).
leiomyoma (1 paper, 2017). A well-circumscribed benign smooth muscle neoplasm characterized by the presence of spindle cells with cigar-shaped nuclei, interlacing fascicles, and a whorled pattern. "In line, R5020, a synthetic progestin acting as a PR agonist, was shown to induce proliferation of leiomyoma cells in vitro, through the phosphorylation of the downstream targets of AKT (FOXO1 and GSK3β)." (PMID 28930160, 2017). "In leiomyoma cells, PRs can rapidly activate the PI3K/AKT pathway and its effectors, such as p-GSK3β and p-FOXO1." (PMID 28930160, 2017).
Leukoencephalopathy (1 paper, 2024). This term describes abnormality of the white matter of the cerebrum resulting from damage to the myelin sheaths of nerve cells. "This study reveals Pyk2/Gsk3β axis activation by mitochondrial translation inhibition suppresses cholesterol gene expression via Srebp2 degradation, offering a novel approach to leukoencephalopathy." (PMID 38719751, 2024). "Improving the mitochondrial translation or effectiveness of Gsk3β inhibitors is a potential therapeutic strategy for leukoencephalopathy." (PMID 38719751, 2024).
macrocephalus (1 paper, 2021). "HDAC1 valproic acid inhibition and GSK3B lithium upregulate the Wnt transcription inhibition and lead to macrocephalus." (PMID 34877571, 2021).
malignant fibrous histiocytoma (1 paper, 2020). "A previous study also reported that undifferentiated sarcoma (or malignant fibrous histiocytoma, MFH) develops from mesenchymal stem cells (MSCs) via inactivation of the Wnt pathway, suggesting a pathogenic role for GSK3β in this tumor type." (PMID 32503133, 2020).
manic episodes (1 paper, 2015). "Moreover, it is found that lithium, a popular treatment for manic episodes, can inhibit glycogen synthase kinase 3β (GSK3β) and facilitate the degradation of NR1D1." (PMID 25789810, 2015).
metastasis (1 paper, 2014). The spread or migration of cancer cells from one part of the body (where they first appeared) to another. "Next, we assessed the potential anti-metastatic effects of GSK-3β inhibition in a xenograft model of experimentally-induced bone metastasis." (PMID 25344861, 2014).
metastatic prostate carcinoma (1 paper, 2013). A carcinoma that arises from the prostate gland and has spread to other anatomic sites. "Interestingly, in metastatic prostate cancer cells DAB2IP appears to directly associate with GSK3β and form a complex with phosphatase 2A and axin, a component of the β-catenin destruction complex." (PMID 24073285, 2013).
microphthalmia (1 paper, 2021). Congenital or developmental anomaly in which the eyeballs are abnormally small. "We showed that complete loss of both GSK3s severely impacts retinal morphology with microphthalmia phenotype, which could be completely rescued with the expression of just one Gsk3α or Gsk3β wild-type (WT) allele." (PMID 34518365, 2021).
Mm (1 paper, 2024). "Additionally, our results demonstrated that SA exerts an antioxidative effect on Mm infection by activating the AMPK-α1/AKT/GSK-3β signaling pathway and upregulating the expression of NRF2/HO-1/NQO-1." (PMID 38399751, 2024).
mouth cancer (1 paper, 2015). "The present study revealed an increased protein expression of GSK3β compared to GSK3α in various types of mouth neoplasms." (PMID 25645517, 2015).
mucoepidermoid carcinoma (1 paper, 2015). A carcinoma morphologically characterized the presence of cuboidal mucous cells, goblet-like mucous cells, squamoid cells, cystic changes, and a fibrotic stromal formation. "The tissue samples of most of the mucoepidermoid carcinoma showed expression of both GSK3α and GSK3β in ductal cells (c, d and q, r and u, v)." (PMID 25645517, 2015). "Mucoepidermoid carcinoma and normal salivary glands exhibited expression of GSK3α and GSK3β, mainly in the ductal cells." (PMID 25645517, 2015).
muscle tumors (1 paper, 2023). "In addition, 25 DPs are related to muscle tumors; 8 DPs (APOE, FCER1A, FCER2, GSK3B, HSPD1, IL6R, MMP7, and RARRES2) are linked to proliferation of muscle cells." (PMID 36918772, 2023).
Myelodysplasia (1 paper, 2024). Clonal hematopoietic stem cell disorders characterized by dysplasia (ineffective production) in one or more hematopoietic cell lineages, leading to anemia and cytopenia. "It is known that genetic deficiency of GSK3β in murine hematopoietic stem cells increases Wnt signaling and produces myelodysplasia, ultimately promoting leukemogenesis in combination with other cooperating events." (PMID 38438856, 2024).
myelofibrosis (1 paper, 2025). A partial or complete replacement of the bone marrow stroma by fibrous tissue. "DB08512 is an experimental compound with no clinical use reported, and Elraglusib (9-ING-41) is a GSK-3β inhibitor in trials for other malignancies (e.g., myelofibrosis) without demonstrated efficacy in AML." (PMID 41301700, 2025).
myocardial diseases (1 paper, 2023). "Circulatory GSK3β is recognized as a biomarker and therapeutic target for diseases, including myocardial diseases." (PMID 37626874, 2023).
neuritis (1 paper, 2022). A neuropathy arising from inflammation of one or more nerves. "SB216763 inhibits the activity of GSK3β and reduces the nuclear activity of the NFKB1 pathway, which alleviates neuritis." (PMID 36290175, 2022).
neutropenia (1 paper, 2019). A decrease in the number of neutrophils found in the blood. "GSK3β inhibition has been responsible for the therapeutic effect of lithium in a number of diseases, such as acute brain injury, chronic neurodegenerative diseases, neutropenia and so forth." (PMID 31349118, 2019).
non-Hodgkin lymphoma (1 paper, 2023). Distinct from Hodgkin lymphoma both morphologically and biologically, non-Hodgkin lymphoma (NHL) is characterized by the absence of Reed-Sternberg cells, can occur at any age, and usually presents as a localized or generalized lymphadenopathy associated with fever and weight loss. "Elraglusib (formerly 9-ING-41) is an ATP-competitive inhibitor of glycogen synthase kinase-3β (GSK3β) undergoing clinical trials for the treatment of various cancers including non-Hodgkin lymphoma (NHL)." (PMID 37316860, 2023).
oligohydramnios (1 paper, 2023). A lower than normal quantity of amniotic fluid in the amniotic sac as compared to normal values. "Human amniotic epithelium cells (hAECs) from pregnant women with normal AFV and isolated oligohydramnios were incubated with 35 μmmol/L Tanshinone IIA or 25 mmol/L LiCl [inhibitor of glycogen synthetic kinase 3β (GSK-3β)]." (PMID 37386378, 2023). "In the hAECs of isolated oligohydramnios, the expression of total GSK-3β was not significantly affected by Tanshinone IIA and LiCl." (PMID 37386378, 2023). "Moreover, the regulation of AQPs expression by Tanshinone IIA in the amniotic epithelial cells of isolated oligohydramnios is independent of GSK-3β." (PMID 37386378, 2023).
pancreatic tubular adenocarcinoma (1 paper, 2024). A tubular adenocarcinoma that involves the pancreas. "In pancreatic tubular adenocarcinoma, dual luciferase reporter and ChIP experiments have demonstrated that YBX1 binds to the promoter of GSK3B, thereby promoting its transcription and leading to elevated levels of GSK3B protein." (PMID 38255791, 2024).
pancreatitis (1 paper, 2017). Inflammation of the pancreas. "More recently, a relationship between GSK3β and ER stress has been evidenced in a pancreatitis model." (PMID 28282906, 2017).